RETN (resistin)
Description:
Hormone that seems to suppress insulin ability to stimulate glucose uptake into adipose cells (By similarity). Potentially links obesity to diabetes (By similarity). Promotes chemotaxis in myeloid cells.
Synonyms: ADSF; FIZZ3; RSTN; RETN1; RENT; XCP1
Tractability: Antibody: its Gene Ontology location is reachable by antibodies, with high confidence; UniProt places it where antibodies can reach, with medium confidence; UniProt predicts a signal peptide or a membrane-spanning region.
Gene: Protein-coding gene on chromosome 19 (7,669,049 to 7,670,455, forward strand). Ensembl gene ENSG00000104918.
Subcellular location: Secreted
Pathways (Reactome):
Gene expression (Transcription): FOXO-mediated transcription of oxidative stress, metabolic and neuronal genes
Immune System: Neutrophil degranulation
Gene Ontology:
Molecular function: protein binding; hormone activity
Biological process: fat cell differentiation; negative regulation of feeding behavior; positive regulation of progesterone secretion; positive regulation of synaptic transmission; response to insulin; response to mechanical stimulus; signal transduction
Cellular component: extracellular exosome; azurophil granule lumen; extracellular region; specific granule lumen
Genetic constraint (gnomAD): Loss-of-function variants: 6 observed, 5.88 expected, observed/expected ratio (o/e) 1.02, 90% interval 0.55 to 1.79. That is too few expected variants to judge how well the gene tolerates losing a copy. Missense variants: 163 observed, 132.29 expected, observed/expected ratio (o/e) 1.23, 90% interval 1.08 to 1.4. Synonymous variants: 62 observed, 56.1 expected, observed/expected ratio (o/e) 1.11, 90% interval 0.9 to 1.37.
Homologues: Orthologues: chimpanzee RETN (98% identical), pig RETN (76% identical), guinea pig RETN (70% identical), rabbit RETN (70% identical), mouse Retn (56% identical), dog RETN (55% identical), rat Retn (54% identical). Paralogues in human: RETNLB (47% identical).
Diseases named in the same sentence as RETN in open-access papers:
RETN is named in the same sentence as 383 diseases in open-access papers, as found by Europe PMC text mining. Sharing a sentence is not in itself a finding about the gene and the disease. The quoted sentences say what the papers report.
Obesity (756 papers, 2004 to 2026). Accumulation of substantial excess body fat. "In RRMS, obesity is associated with elevated serum and CSF levels of pro-inflammatory cytokines such as IL-6 and adipokines, including leptin, resistin, and chemerin, alongside reduced levels of the anti-inflammatory adipokine adiponectin." (PMID 41562846, 2026). "Another study has shown a distinct structural similarity between the C-terminus cysteine-rich domain (CRD) of PCSK9 and the resistin homotrimer, a pro-inflammatory factor associated with obesity." (PMID 40076547, 2025). "Although adiponectin and resistin have opposite effects, they play an important role in low-grade inflammation, obesity, and morbidities associated with obesity." (PMID 39796247, 2025). "This review explores the role of adipokines, mainly resistin and adiponectin, in mediating the effects of obesity-associated alterations, including low-grade chronic inflammation and impaired metabolism, on brain function." (PMID 41155642, 2025). "Resistin, like visfatin, has pro-inflammatory effects and is associated with insulin resistance, obesity, diabetes, atherosclerosis and chronic inflammation." (PMID 40869389, 2025). "Polymorphisms in the resistin gene (RETN), such as the promoter variant rs1862513, are associated with elevated serum resistin levels, obesity susceptibility, insulin resistance, and coronary artery disease severity." (PMID 41347124, 2025). "The recent meta-analyses acknowledged that there is a remarkable correlation between the enhanced expression of resistin and the incidence of cancers associated with obesity." (PMID 40076482, 2025). "In obese and hyperglycemic mice, the administration of anti-resistin antibody reduced glucose level and improved insulin sensitivity, indirectly suggesting that elevated resistin levels played a causative role in the high risk of obesity-related T2DM." (PMID 39812542, 2025). "A characteristic feature of obesity is the alteration in lipid levels, which is linked to increased resistin levels." (PMID 40040878, 2025). "Mechanistically, resistin mediates a substantial proportion of the obesity-associated atrial fibrillation risk, positioning it as a critical link between metabolic dysfunction and electrical instability." (PMID 41347124, 2025). "This genetic link underscores resistin’s heritable contribution to obesity-related inflammation and cardiovascular risk, independent of adiposity measures." (PMID 41347124, 2025). "Chronic myristic acid supplementation has been shown to worsen obesity-associated insulin resistance, and this effect is partly mediated by increased adipose tissue inflammation and increased resistin secretion." (PMID 41464244, 2025). "Alterations in resistin-induced microbicidal activity and apoptosis have previously been reported in colostrum macrophages from mothers with diabetes-associated obesity, as well as changes in cytokine profiles and metabolites in colostrum from obese mothers." (PMID 41301907, 2025). "On a similar note, a state of obesity by itself is a risk factor of periodontal destruction and it increases the release of adipokines (such as leptin and resistin) and destructive inflammatory cytokines such as IL-6." (PMID 41396032, 2025). "Both sdLDL and resistin are significant biochemical causes of obesity, with sdLDL having a stronger effect in men." (PMID 41315571, 2025). "Resistin (RETN), a small secretory molecule, was initially implicated as a potential link between obesity and diabetes." (PMID 40002704, 2025). "A recent meta‐analysis linked increased plasma resistin levels to a higher incidence of obesity‐related cancers, including breast, endometrial, and colorectal cancer; however, resistin levels should not be considered predictive factors." (PMID 39764565, 2025). "This study suggests that resistin and sdLDL levels are the primary cause of dyslipidemia and metabolic dysregulation in obesity." (PMID 41315571, 2025).
Obesity (continued). "In our study, we observed an increase in resistin levels in the psoriasis patients with both normal BMI and associated overweight and obesity." (PMID 40095687, 2025). "Adipose tissue also produces a variety of adipokines and proinflammatory cytokines linked to obesity-associated male infertility, including leptin, adiponectin, resistin, ghrelin, TNF-alpha, IL-1β and IL-6." (PMID 40140188, 2025). "Among them, obesity, BMI, body fat percentage, waist circumference, hip circumference, and resistin were risk factors, while apolipoprotein A1 (apoA1), high-density lipoprotein cholesterol (HDL-C), and nerve growth factor (NGF) were protective factors." (PMID 39050546, 2024). "Pro-inflammatory adipokines, leptin, and resistin are positively associated with body weight, fat mass, insulin resistance, obesity, and type 2 diabetes." (PMID 38612666, 2024). "Currently, resistin inhibitors like masoprocol are being regarded as promising medications for treating obesity and its associated metabolic and CVDs." (PMID 39335642, 2024). "Adipokine resistin, believed to be associated with obesity, insulin resistance, and diabetes, is highly expressed in DCM." (PMID 38664790, 2024). "Obesity is considered a risk factor for the development of certain cancers and epidemiological studies suggest a link between resistin and cancer, as serum resistin levels are elevated in several cancers, including breast and colorectal." (PMID 39184804, 2024). "Adiponectin increase and resistin decrease acted as endocrine mediators driving the remission of cardiometabolic risk biomarkers in individuals with obesity following Roux-en-Y gastric bypass." (PMID 38399430, 2024). "Although various hormones and adipokines are linked to obesity, ghrelin and resistin are two molecules being actively investigated for possible roles in the mechanism of obesity." (PMID 38833355, 2024). "Although various hormones and adipokines, including ghrelin and resistin, are linked to obesity, studies analyzing the changes in fasting ghrelin and resistin levels in patients following one anastomosis gastric bypass (OAGB) are lacking." (PMID 38833355, 2024). "Resistin is also an adipocytokine, and excessive secretion of resistin due to obesity is thought to be a cause of diabetes." (PMID 39200235, 2024). "We also demonstrated that the increase in serum adiponectin levels, along with the reduction in resistin, appear to be endocrine mechanisms that mediate the reduction in the risk of obesity-associated diseases." (PMID 38399430, 2024). "Although resistin has been implicated as a link between obesity and insulin resistance in rodents, there has been much controversy regarding the role of resistin in inducing insulin resistance in humans." (PMID 39050819, 2024). "Serum concentrations of adipokines, leptin, adiponectin, visfatin and resistin and inflammatory markers associated with low-grade inflammation in obesity, CRP, IL-6, sE-selectin, sVCAM, sPECAM and VEGF, were similar in both groups, regardless of CK-18." (PMID 37189422, 2023). "Hyperleptinemia and an increased level of resistin are associated with obesity and result in impaired glucose metabolism and IR." (PMID 37630842, 2023). "Both surgical and dietary weight loss reverted obesity-driven elevation of leptin and resistin levels, while only dietary weight loss reverted elevation of plasminogen activator inhibitor 1 (PAI-1)." (PMID 37698918, 2023). "Then abnormal production and secretion of adipokines (including leptin, adiponectin, resistin, etc.)are also thought to play an important role in the association between obesity and systemic inflammation." (PMID 36790552, 2023). "The role of resistin was linked to the occurrence of obesity, insulin resistance, and diabetes in mice." (PMID 36978817, 2023).
Obesity (continued). "Inflammatory cytokines or LPS can induce resistin expression in monocytes/macrophages, and as a result, resistin was designated as a pro-inflammatory factor associated with low-grade inflammation in obesity." (PMID 37238973, 2023). "Obesity, atherosclerosis, cardiovascular events, and autoimmune diseases have been associated with elevation in serum resistin levels." (PMID 37355349, 2023). "While resistin has been associated with insulin resistance, obesity, and diabetes, it appears to play a more substantial role in inflammation." (PMID 37834432, 2023). "In this regard, resistin has been implied as a risk factor for dementia since it antagonizes insulin action and promotes inflammation in obesity." (PMID 37732123, 2023). "Systemic inflammatory factor (TNF-α) and resistin were indicated to be associated with sarcopenia and obesity in a previous study." (PMID 37853348, 2023). "Resistin is an 11 kDa protein encoded on chromosome 8, which was once classified as a unique signaling molecule in-between obesity and type 2 diabetes mellitus." (PMID 38149100, 2023). "The main adipokines associated with development of obesity are leptin, adiponectin, resistin, TNF-alpha, and IL-6." (PMID 37629396, 2023). "Obesity causes hypothalamic–pituitary–adrenal dysregulation and changes in the plasma levels of cortisol, leptin, adiponectin, resistin, and insulin, which are hormones involved in emotional and mood regulation." (PMID 37046297, 2023). "The reduction of obesity-associated pro-inflammatory mediators (e.g., FFAs, TNFα, resistin, and AGEs), and the improvement in the gut–brain axis represent alternative paths through which regular exercise can mitigate hypothalamic inflammation." (PMID 36829858, 2023). "Taken together, our data suggest that chronic administration of MA in diet exacerbates obesity-associated insulin resistance and this effect is mediated in part, via increased AT inflammation and increased secretion of resistin." (PMID 35740864, 2022). "Dysregulated adipocytokines and adipokines in obesity, such as leptin, resistin, TNF, and IL-6, are associated with the vascular dysfunction process." (PMID 35883829, 2022). "Obesity has a strong association with immune cell abnormalities, and adipose tissue produces and releases various adipokines (leptin, adiponectin, resistin and visfatin) and pro-inflammatory cytokines (TNF-α, IL-4, IL-6)." (PMID 36574392, 2022). "Second, five proteins (CCL25, GRIA4, HBEGF, NPPA and RETN) were also considered because they have been reported to be associated with obesity." (PMID 35879730, 2022). "Insulin resistance caused by obesity is related to the development of a chronic low-grade inflammatory state and the action of adipokines, such as leptin, resistin, TNF-α, IL-6, MCP-1, and CRP." (PMID 36262532, 2022). "Adipokine human Resistin (hResistin), is known to be associated with insulin resistance and secrete low-grade pro-inflammatory cytokines in obesity." (PMID 35624126, 2022). "Since resistin was discovered, various studies have investigated its association with several metabolic diseases, such as obesity, metabolic syndrome, insulin resistance, diabetes, and other related diseases." (PMID 36686437, 2022). "Further, we show that obesity-related IR is enhanced in mice receiving the MA-supplemented diet and it was associated with an increase in circulating resistin, an adipokine mediating IR." (PMID 35740864, 2022). "Although resistin plays an important role in the association of diabetes and obesity, little is known about the influence of this hormone on the immunological components present in human milk." (PMID 36289594, 2022). "Elevated resistin concentrations have been associated with obesity and are excellent markers for the prognosis of breast cancer." (PMID 36262532, 2022). "As a proinflammatory adipokine, resistin is associated with several cardiometabolic phenotypes, including obesity, diabetes, and hyperlipidemia." (PMID 35457109, 2022).
Obesity (continued). "Its pathogenesis is mainly mediated by obesity-associated hyperinsulinemia, increased circulating levels of leptin, resistin, and various cytokines by altering the gut microbial flora and oxidative stress." (PMID 36059323, 2022). "(2013) investigated the role of RETN variants (rs1862513, rs3745367 and rs3745369) in obesity and bone mineral density and were unable to find any association between these variants and bone related parameters." (PMID 35992125, 2022). "Adipokines including leptin, adiponectin and resistin have been linked to risk of obesity-related cancers potentially through low-grade chronic inflammation pathways." (PMID 34876619, 2021). "Obesity is clearly associated with the levels of hormones, such as leptin, adiponectin and resistin secreted from adipose tissue." (PMID 33830560, 2021). "In contrast to its established pro-inflammatory effects, the evidence for resistin’s associations with obesity, insulin resistance and glucose regulation remains weak." (PMID 33716966, 2021). "While there is a range of potential pathways associated with CD development in those affected by obesity, the presence of mesenteric fat increases resistin secretion from macrophages and leukocytes." (PMID 33401588, 2021). "Increased resistin levels are associated with the pathogenesis of obesity-associated insulin resistance and exert pro-inflammatory effects." (PMID 34684622, 2021). "In humans, several studies found an association between resistin and obesity, while weight loss was accompanied by a reduction in resistin level." (PMID 34202323, 2021). "Some adipokines, such as leptin, resistin, and visfatin, which are overproduced in obesity and widely implicated in different stages of cancer, promote cellular glucose and lipid metabolism." (PMID 33535537, 2021). "It has been reported that the association between resistin and obesity is stronger in women than in men, although opposite results were reported in other studies." (PMID 34496965, 2021). "Another adipokine, resistin, is increased in adipocytes under obesity-associated metabolic conditions, and the expression is upregulated in the breast tissue of diet-induced obese mice." (PMID 34944905, 2021). "Multiple studies have shown that obesity-related serious diseases, such as cardiovascular disease and malignancies, are associated with elevated resistin levels." (PMID 34659568, 2021). "A preclinical study demonstrated that adipocytes under obesity-associated metabolic conditions have an increased secretion of resistin." (PMID 33738261, 2021). "While in some species, like rodents, plasma resistin concentrations increase with obesity and metabolic syndrome, in other species, like humans, plasma resistin concentrations increase preferentially when associated with inflammatory problems." (PMID 35011183, 2021). "The adipokine resistin is linked with obesity, inflammation and various cancers, including breast cancer." (PMID 32226495, 2020). "Excessive fat, or obesity, is associated with a decrease in adiponectin and/or an increase in leptin, resistin, and tumor necrosis factor-alpha." (PMID 32498328, 2020). "The adipokines adiponectin, resistin, and leptin are cytokines that have been associated with a number of health-related conditions related to obesity-induced inflammation." (PMID 33467260, 2020). "We also reported that DNAJC27 was positively associated with obesity biomarkers such as leptin and resistin." (PMID 32733386, 2020). "Previous studies showed a positive association between obesity and leptin and resistin concentrations." (PMID 33007981, 2020). "Adenylate cyclase-associated protein 1 (CAP1), an actin regulatory protein and functional receptor for the obesity-associated adipokine resistin, has been implicated with inferior cancer prognosis." (PMID 32560703, 2020).